PLD1 (phospholipase D1)
Diseases named in the same sentence as PLD1 in open-access papers (continued):
Sharing a sentence is not in itself a finding about the gene and the disease.
glioma (7 papers, 2014 to 2023). A benign or malignant brain and spinal cord tumor that arises from glial cells (astrocytes, oligodendrocytes, ependymal cells). "Overall, these data suggested that PLD1 overexpression was a risk factor for the migration and proliferation of glioma." (PMID 28915652, 2017). "In the present study, we learned the role of lipid metabolism in glioma on the cell line and tissues by studying PLD1, a critical enzyme that implicated in lipids metabolism." (PMID 28915652, 2017). "Moreover, PLD1 overexpression promotes invasion and migration and function as a risk factor for Chinese glioma patients." (PMID 34238129, 2021). "Furthermore, we showed in COX regression assay that PLD1 was a risk factor for glioma (p = 0.018, HR = 0.461, 95% CI = 0.243–0.887)." (PMID 28915652, 2017). "Meanwhile, since MMP9 faciliates migration of various cancers, we then examined whether it also implicated in PLD1-resultant migration of glioma cells." (PMID 28915652, 2017). "Moreover, we showed in the COX regression assay that that PLD1 was a risk factor for glioma." (PMID 28915652, 2017). "- Through PLD-1 suppression by QUE, glioma cell proliferation is achieved- QUE suppressed PLD1 expression through inhibition of NFkB transactivation- QUE inhibited tumor cell invasion by reducing MMP-2 activity." (PMID 36986827, 2023). "In two separate studies, CAPE proved active in suppressing the invasion and proliferation of glioma cells by the down-regulation of PLD1 and 5-LO expression." (PMID 33525407, 2021). "Another study demonstrated that CAPE suppressed the invasion and proliferation of glioma cells by the down-regulation of phospholipase D1 (PLD1) expression at the transcriptional level." (PMID 33525407, 2021). "Several reports have shown that PLD1 upregulates the expression of MMPs in glioma, melanoma, and fibrosarcoma cells, which, in turn, promotes their migration and invasion." (PMID 32074974, 2020). "Subsequently, in order to evaluate the role of PLD1 in glioma, U87 cell was selected to construct PLD1-knockdown cells since it showed higher PLD1 expression compared to U251." (PMID 28915652, 2017). "In summary, our findings had revealed that PLD1 overexpression confers a poor prognosis for patients with glioma." (PMID 28915652, 2017). "Meanwhile, we also found that PLD1 expression was positively correlated with differentiation of glioma cells, and it confers a poor prognosis for the patients." (PMID 28915652, 2017). "In the present study, the expression and biological significance of PLD1 were investigated on the clinical samples of glioma as well as the cell lines using immunohistochemistry and western blot." (PMID 28915652, 2017). "To confirm the role of PLD1 in glioma, we then examined its expression and function in cell lines of glioma." (PMID 28915652, 2017). "Considering the fact that PLD1 overexpression confers a poor prognosis for glioma, we examined the prognostic value of PLD1 in glioma using COX regression model." (PMID 28915652, 2017). "Of note, there were also studies focused on the role of PLD1 in glioma, they put forward that PLD1 was overexpression in glioma cell lines, and that PLD1 was responsible for aggressive phenotype." (PMID 28915652, 2017). "To further confirm the role of PLD1 in glioma proliferation and migration, we pharmacologically inhhibited PLD1, and found that both U87 and U251 cells cells exhibited decreased proliferation and migration." (PMID 28915652, 2017). "As to glioma, shattered reports showed that PLD1 and its isoform PLD2 were upregulated in cell lines of glioma associating with increased capacities of invasion and migration." (PMID 28915652, 2017). "Since PLD1 serves as a pro-tumoral factor for glioma, further studies are needed to determine the pathological mechanism of PLD1 in glioma so as to reveal novel therapeutic targets for the lethal disease." (PMID 28915652, 2017).
glioma (continued). "Consistently, in glioma cells, the overexpression of PLD-1 and PLD-2 enhanced the expression of antiapoptotic genes." (PMID 25489735, 2014). "As to glioma, Park MH and colleague revealed that quercetin could inhibit the invasion and proliferation of glioma cells via abolishes PLD1." (PMID 28915652, 2017). "Consistently, we also showed that PLD1 was overexpression in glioma cell lines." (PMID 28915652, 2017). "Similarly, our study confirmed the positive role of PLD1 in glioma development from both the cellular and histological levels." (PMID 28915652, 2017). "Overall, our data proposed that PLD1 overexpression was pro-tumoral in glioma, and that targeted inhibition PLD1 might represent a novel approach for glioma management." (PMID 28915652, 2017). "Meanwhile, we also showed that PLD1 overexpression could facilitate the proliferation and migration of glioma cells." (PMID 28915652, 2017). "Since CyclinD1 and CDK4 facilitate cell proliferation in various cells, we then investigated whether they involved in PLD1-resultant proliferation of glioma cells." (PMID 28915652, 2017). "Taken together, our study suggested that PLD1 was pro-tumoral in glioma, and that further studies were urgently needed so as to define whether it was a novel therapeutic target for the disease." (PMID 28915652, 2017). "In the present study, we showed that PLD1 was overexpression in clinical samples of glioma." (PMID 28915652, 2017). "This verr in combine with our data suggedted that targeted inhibition of PLD1 might represent a novel direction for the management of glioma." (PMID 28915652, 2017). "We found that upregulated PLD1 was assiciated with poor differentiation and prognosis for glioma." (PMID 28915652, 2017). "Consistently, we found that PLD1 was overexpression in glioma cell lines, and it could facilitate the proliferation and migration." (PMID 28915652, 2017). "Therefore, by decreasing the level of PLD-1, Que might reduce the tumor activity through the reduction of proliferation and invasion of gliomas." (PMID 36986827, 2023). "In addition, we further showed that PLD1 could facilitate the proliferation and migration of glioma cell lines." (PMID 28915652, 2017). "Additionally, we also evaluated the role of PLD1 in glioma proliferation and migration." (PMID 28915652, 2017). "Finally, functional analysis showed that PLD1 overexpression could facilitate the propagation of glioma cells in a manner dependent on CyclinD1 as well as CKD4, and promote the migration of glioma by upregulating MMP9 secretion." (PMID 28915652, 2017).
Alzheimer disease (6 papers, 2017 to 2022). A progressive, neurodegenerative disease characterized by loss of function and death of nerve cells in several areas of the brain leading to loss of cognitive function such as memory and language. "Alterations that impact PLD1, or that occur elsewhere and influence alternative splicing and tendency to aggregate inside cells, are also linked with familial cervical dystonia and Alzheimer’s disease, and other mutations with benign essential blepharospasm." (PMID 35289833, 2022). "Similarly, both PLD1 and PLD2 reportedly regulate macrophage phagocytosis, Alzheimer’s disease, and tumor growth." (PMID 32971863, 2020). "Additionally, the generation of the myc-PLD1 and HA-PLD2 knockin mouse lines will be beneficial to a wide range of studies regarding PLDs, from their antiapoptotic role in cancer, to their potential as a therapeutic target for Alzheimer’s disease." (PMID 35764123, 2022). "However, different roles of PLD1 and PLD2 in Alzheimer Disease have been found." (PMID 28219337, 2017).
cervical cancer (6 papers, 2021 to 2022). A primary or metastatic malignant neoplasm involving the cervix. "Introduction of siRNAs against LINC00511, RXRA, or PLD1 led to repression of proliferation and promotion of autophagy and apoptosis of cervical cancer cells." (PMID 35456001, 2022). "LINC00511 was shown to bind RXRA, and overexpression of LINC00511 increased PLD1 mRNA and protein expression in cervical cancer cells." (PMID 35456001, 2022). "LINC00511 contributes to RXRA-mediated transcriptional activation of PLD1 as an oncogenic lncRNA in cervical cancer by recruiting the transcription factor RXRA." (PMID 35771155, 2022). "This study aimed to further investigate the effect of PLD1 on the biological characteristics of human cervical cancer (CC) cell line, CASKI and the potential related molecular mechanism." (PMID 35775110, 2022). "LncRNA LINC00511 and PLD1 expression were elevated in cervical cancer cells and tissues." (PMID 35456001, 2022). "LINC00511 is upregulated in cervical cancers and could promote PLD1 expression by enriching RXRA to the promoter region of PLD1 and activating PLD1 promoter activity, thus enhancing proliferation and inhibiting the autophagy and apoptosis of cervical cancer cells." (PMID 34803512, 2021). "For example, we detected elevated levels of phospholipase D1 (PLD1), a key enzyme involved in lipid metabolism, indicating that abnormal lipid metabolism might be involved in the tumorigenesis and progression of cervical cancer." (PMID 34900703, 2021). "The expression level of PLD1 is not affected by the upregulation or downregulation of DUSP7, and the effect of PLD1 on the progression of cervical cancer is not dependent on the activity status of DUSP7." (PMID 34435746, 2021).
melanoma (6 papers, 2014 to 2026). A malignant, usually aggressive tumor composed of atypical, neoplastic melanocytes. "The vascularization of melanoma or lung tumors from phospholipase D1 (PLD1) knockout mice was significantly reduced as a result of PLD downregulation in the tumor environment." (PMID 27851813, 2016). "In addition, PLD1 plays a role in melanoma growth and metastasis in vivo; a significant reduction in tumor metastasis was observed in the wild-type or PLD1 knockout mice following CAY10594 inhibitor treatment." (PMID 35127525, 2021). "Thus, TRPA1 and PLD1 are potential targets for therapeutic intervention in melanoma." (PMID 42121861, 2026). "Melanoma cell lines, but not primary melanocytes, have high levels of PLD activity that is dependent on PKC, Rho and phorbol ester, suggesting that it is PLD1 rather than PLD2 that is involved in cancer progression." (PMID 24103483, 2014).
gastric cancer (5 papers, 2015 to 2024). A primary or metastatic malignant neoplasm involving the stomach. "Thus, cagA-positive H. pylori-induced NF-κB activation might increase the risk of gastric cancer via the upregulation of PLD1 expression." (PMID 38945955, 2024). "Infection of gastric cancer cells with cagA-positive H. pylori leads to selective induction of PLD1 expression via cagA-dependent activation of NF-κB35." (PMID 38945955, 2024). "PLD1 expression and IκBα phosphorylation are aberrantly increased in H. pylori-infected human gastric cancer tissues, and rebamipide, a mucosal-protective antiulcer agent, abolishes H. pylori cagA-induced PLD1 expression via inhibition of NF-κB binding to the PLD1 promoter." (PMID 38945955, 2024). "Thus, targeting PLD1 may suppress chemoresistance via downregulation of the Wnt/β‐catenin signaling pathway in various cancers, including GBM, CRC and gastric cancer." (PMID 38945955, 2024).
glioblastoma (5 papers, 2014 to 2023). The most malignant astrocytic tumor (WHO grade IV). "Recent findings also highlighted the interesting role of the PLD1 isoform, in the physiology of GSCs and especially in recurrent glioblastoma." (PMID 37238668, 2023). "Phospholipase D1 conferred resistance to temozolomide in CD44High glioblastoma stem cells and increased their self‐renewal capacity and maintenance." (PMID 32725633, 2020). "Here, we show that phospholipase D1 is elevated in CD44High glioblastoma stem cells and in glioblastoma, especially recurring glioblastoma." (PMID 32725633, 2020). "Genetic and pharmacological targeting of phospholipase D1 attenuated glioblastoma stem cell‐derived intracranial tumors of glioblastoma using the microRNAs, and improved survival." (PMID 32725633, 2020). "We further examined whether CTR-GNPs can suppress the protein expression of MMP-2/-9 and PLD1/2 in human U87 glioblastoma cells." (PMID 32074974, 2020). "Together, these findings indicate that phospholipase D1 inhibition might overcome resistance to temozolomide and represents a potential treatment strategy for glioblastoma." (PMID 32725633, 2020). "In detail, PLD1 inhibition sensitizes GSCs to the alkylating agent and reduces glioblastoma tumorigenesis, pointing out the aim of the current research on glioblastoma, which is focused on any novel therapy that could address GSC-driven tumor recurrence and resistance to TMZ." (PMID 37238668, 2023). "Phospholipase D1 (PLD1) is a transcriptional target of histone deacetylase (HDAC) inhibitors and confers resistance to HDAC inhibitor in glioblastoma (GBM)." (PMID 32869317, 2021). "Phospholipase D1 elevation positively correlated with the level of CD44 and poor prognosis in glioblastoma patients." (PMID 32725633, 2020). "Treatment solely with temozolomide produced no benefits on the glioblastoma, whereas in combination, phospholipase D1 inhibition sensitized glioblastoma stem cells to temozolomide and reduced glioblastoma tumorigenesis." (PMID 32725633, 2020). "CTR-GNPs decreased the mRNA levels of MMP-2/-9 and PLD1 in human U87 glioblastoma cells treated with or without PMA." (PMID 32074974, 2020). "The human cerebrum, astrocytes, neuronal progenitor cells, NTera2 teratocarcinoma-derived neurons, SK-N-SH neuroblastoma, IMR-32 neuroblastoma, U-373MG glioblastoma, T98 glioblastoma, and HMO6 immortalized microglia constitutively expressed PLD1, PLD2, and PLD3 transcripts (lanes 1, 3 to 10)." (PMID 25478031, 2014). "Temozolomide significantly upregulated the expression of phospholipase D1 in the low and moderate CD44 populations of glioblastoma stem cells, but not in the CD44High population in which phospholipase D1 is highly expressed." (PMID 32725633, 2020). "Importantly, treatment with CTR-GNPs significantly decreased the levels of metalloproteinase (MMP)-2/-9 and phospholipase D1 (PLD1) and protein but not PLD2, which is involved in the modulation of migration and the invasion of glioblastoma cells." (PMID 32074974, 2020).
pancreatic cancer (5 papers, 2016 to 2024). "In the pancreatic cancer pathway, for example, mutation-activated KRAS signaling through RalGDS involves PA via phospholipase D1/2 (PLD1/2)." (PMID 39676871, 2024). "Prior studies have shown that the correlated Sp1 and PLD1 had a synergic effect in promoting pancreatic cancer, which indicates that Sp1 may also be elevated and have a pro-tumoral function in osteosarcomas." (PMID 29088790, 2017). "The quantification showed that mRNA levels of all candidate genes were significantly higher in pancreatic cancer samples compared to controls (p < 0.0001 in FKBP1A, p < 0.0001 in PLD1, and p = 0.0002 in PSMA4)." (PMID 38570626, 2024). "Our results revealed high mRNA expression levels in WBCs of pancreatic cancer patients in all selected genes, including FKBP1A (p < 0.0001), PLD1 (p < 0.0001), and PSMA4 (p = 0.0002)." (PMID 38570626, 2024). "To further confirm the positive correlation between in Sp1 and PLD1 in PDAC, we investigated their expression and correlation in pancreatic duct epithelial (HPDE) cells and pancreatic cancer cell." (PMID 27713167, 2016). "Amongst them, PLD1, EGFR, ST3GAL3 and ARF6 mediate the progression of pancreatic cancer." (PMID 33493138, 2021).
Arterial thrombosis (4 papers, 2016 to 2020). The formation of a blood clot inside an artery. "This suggests that PLD1 deficiency might protect against arterial thrombosis and platelet-mediated responses upon inflammation." (PMID 29968773, 2018). "In platelets, PLD1 plays an important role in glycoprotein (GP)Ib-mediated integrin activation and cell adhesion, and genetic deletion of PLD1 protects mice from arterial thrombosis and ischemic-dependent diseases like ischemic brain infarction." (PMID 32370031, 2020). "Deficiency of both PLD isoforms PLD1 and PLD2 as well as pharmacological inhibition of the enzymatic activity of PLD with the PLD inhibitor FIPI protected mice from arterial thrombosis and ischemic brain infarction." (PMID 30555342, 2018). "Previous studies indicate that of deletion of Pld1 and Pld2 protects against development of arterial thrombosis and ischemic stroke." (PMID 27299737, 2016). "However, deletion of PLD1 and PLD2 in mice is protective against arterial thrombosis and ischemic stroke." (PMID 27299737, 2016).
autoimmune disease (4 papers, 2010 to 2022). A disorder resulting from loss of function or tissue destruction of an organ or multiple organs, arising from humoral or cellular immune responses of the individual to their own tissue constituents. "In conclusion, our data suggest that PLD1 may represent a novel therapeutic target for suppressing immune response, inflammation, and bone loss in autoimmune diseases." (PMID 32370217, 2020). "Pld1 inhibitors reportedly promote Treg differentiation in vitro to improve the validation response in autoimmune diseases; the effect of Spin1 on the proliferation and migration of tumor cells has been demonstrated in most tumor studies whereas studies on immune function have been rarely reported." (PMID 35874774, 2022). "Notably, PLD1 had been demonstrated to play an important role in autoimmune diseases." (PMID 32670393, 2020). "Phospholipase D1 (PLD1) plays a crucial role in various inflammatory and autoimmune diseases." (PMID 32370217, 2020). "Thus, our findings indicate that the targeting of PLD1 can ameliorate CIA by modulating the imbalance of Treg and Th17 cells and suppressing osteoclastogenesis, which might be a novel strategy to treat autoimmune diseases, such as RA." (PMID 32370217, 2020). "Notably, the expression of PLD1 but not PLD2, is upregulated in various inflammatory and autoimmune diseases, including acute pancreatitis, peritonitis, RA, and Alzheimer disease." (PMID 32370217, 2020).
diabetes (4 papers, 2010 to 2020). "Over-expression of phosphoprotein enriched in diabetes/phosphoprotein enriched in astrocytes (PED/PEA-15) causes insulin resistance by interacting with the D4 domain of phospholipase D1 (PLD1)." (PMID 23585839, 2013). "In conclusion, our data suggest that deficiency of PLD1 or PLD2 activity promotes development of overweight and diabetes." (PMID 27299737, 2016). "Accordingly, we suggest that the physiological interaction between AMPK and PLD1 may provide clues to solving problems in metabolic syndromes such as diabetes." (PMID 20231899, 2010). "There are six isoforms of PLD, PLD1-6, of which PLD1 and PLD2 isoforms exhibit the ability to hydrolyze phospholipids and these two isoforms have been widely recognized in several human pathophysiologies including cancer, hypertension, neurodisorders, diabetes, and acute lung injury." (PMID 32549377, 2020).
Insulin resistance (4 papers, 2013 to 2016). Increased resistance towards insulin, that is, diminished effectiveness of insulin in reducing blood glucose levels. "Interference with PLD1 function, via expression of a catalytically inactive allele or via selective loss of PLD1 through RNAi targeting, leads to insulin resistance with respect to Glut4 trafficking and glucose uptake." (PMID 26089893, 2015). "Moreover, increased adiposity and high lipid levels in circulation promote insulin resistance and glucose intolerance in both Pld1-/- and Pld2-/- animals." (PMID 27299737, 2016). "Herein, we used Pld1−/− mice to investigate the role of PLD1 in NAFLD and its consequent insulin resistance." (PMID 27976696, 2016). "Nevertheless, the precise roles of PLD1 and its product, PA in NAFLD and insulin resistance have not been examined." (PMID 27976696, 2016).